KRT85 (keratin 85)
Description:
Structural component of intermediate filaments in the hair follicle. As a type II hair keratin, participates in the formation of keratin intermediate filament networks by forming obligate heterodimers with type I hair keratins. Expressed at early stages of hair differentiation in matrix cells and later in cuticle-forming cells, where it contributes to the structural integrity and mechanical resilience of the hair shaft.
Synonyms: K85; KRTHB5; Hb-5; ECTD4; HB5; hHb5
Tractability: PROTAC: UniProt records ubiquitination sites on it; ubiquitination databases record sites on it.
Target class: Structural protein
Gene: Protein-coding gene on chromosome 12 (52,360,006 to 52,367,481, reverse strand). Ensembl gene ENSG00000135443.
Pathways (Reactome):
Developmental Biology: Formation of the cornified envelope; Keratinization
Gene Ontology:
Molecular function: protein binding; structural constituent of skin epidermis; structural molecule activity
Biological process: epidermis development; intermediate filament organization; keratinization
Cellular component: extracellular region; cytosol; keratin filament
Genetic constraint (gnomAD): Loss-of-function variants: 39 observed, 57.27 expected, observed/expected ratio (o/e) 0.68, 90% interval 0.53 to 0.89. The upper end of that interval is the gene's LOEUF score, 0.89, which puts it in group 3 of 6, group 1 being the genes least tolerant of losing a copy. Missense variants: 668 observed, 719.18 expected, observed/expected ratio (o/e) 0.93, 90% interval 0.87 to 0.99. Synonymous variants: 291 observed, 291.26 expected, observed/expected ratio (o/e) 1, 90% interval 0.91 to 1.1.
Homologues: Orthologues: chimpanzee KRT85 (99% identical), macaque KRT85 (99% identical), dog KRT85 (94% identical), pig KRT85 (94% identical), guinea pig KRT85 (93% identical), mouse Krt85 (93% identical), rat Krt85 (92% identical), rabbit KRT85 (73% identical). Paralogues in human: KRT83 (80% identical), KRT86 (80% identical), KRT81 (80% identical), KRT84 (63% identical), KRT82 (58% identical), KRT5 (52% identical), KRT6A (51% identical), KRT6C (51% identical), KRT6B (51% identical), KRT75 (50% identical), KRT3 (49% identical), KRT76 (48% identical), and 56 more.
Diseases named in the same sentence as KRT85 in open-access papers:
KRT85 is named in the same sentence as 15 diseases in open-access papers, as found by Europe PMC text mining. Sharing a sentence is not in itself a finding about the gene and the disease. The quoted sentences say what the papers report.
ectodermal dysplasia (2 papers, 2021 to 2023). "Given that the ectodermal dysplasia associated with KRT85 is a recessive condition, that a variant was identified on only one allele and that it is not clearly pathogenic, this patient's condition remains unsolved (Family 5)." (PMID 37361548, 2023).
alopecia areata (1 paper, 2020). Loss of scalp and body hair involving microscopically inflammatory patchy areas. "In alopecia areata (AA) lesional skin, Krt85 and Krt86 were significantly repressed." (PMID 32028879, 2020).
breast tumours (1 paper, 2015). "We found that all ten EMT-related genes were frequently methylated in primary breast tumours, i.e. CLDN18 (100 %), KRT85 (100 %), MIR127 (100 %), MIR433 (100 %), MIR23b (60 %), KRT83 (100 %), MST1R (60 %), BVES (60 %), CLDN6 (50 %) and HOXD10 (55 %)." (PMID 26052355, 2015).
colon cancer (1 paper, 2022). "The expression of KRT85 was found to be associated with overall survival in subjects with colon cancer." (PMID 35574500, 2022).
hypotrichosis 8 (1 paper, 2023). Any hypotrichosis in which the cause of the disease is a mutation in the LPAR6 gene. "In addition, some paralog genes Krt25, Krt27, Krt72, Krt75, and Krt85, which also participate in the formation of keratin intermediate filaments in the IRS, could be related to Woolly Hair, Autosomal Recessive 3, and Hypotrichosis 8, which were significantly decreased in Krt71–KO mice." (PMID 37443815, 2023).
Nail dystrophy (1 paper, 2022). Onychodystrophy (nail dystrophy) refers to nail changes apart from changes of the color (nail dyschromia) and involves partial or complete disruption of the various keratinous layers of the nail plate. "The mutation of KRT85 can cause sparse to complete absence of hairs and nail dystrophy." (PMID 36423088, 2022).
Rb (1 paper, 2019). "This is the first study suggesting that these genes, FGFR4, NQO1, ACADS CX3CR1, GBE1, KRT85, and TYR genes, may play a role in the etiology of Rb." (PMID 31207142, 2019).
tumor (2 papers, 2023 to 2025). "The strongest SPOT intensity was found to be the positive control (KIAA1614568 − 583), followed by a Rx[LI]xG containing peptide from Keratin-85 (KRT8541 − 55), a SSPxxL[LM] containing peptide from the tumour protein 63 (TP63608 − 622), and the USP21156 − 171 peptide that contains the full motif." (PMID 40329301, 2025).
KRT85 also shares sentences with these, for which no sentence is quoted: cancer (2 papers); adenoma (1); breast carcinoma (1); cardiovascular disease (1); ectodermal dysplasia hair and nail type 7 (1); Oligodontia (1); Woolly hair (1).